MIR1244-3 (microRNA 1244-3)
Synonyms: hsa-mir-1244-3
Gene: MicroRNA gene on chromosome 12 (9,239,467 to 9,239,551, reverse strand). Ensembl gene ENSG00000283429.
Homologues: Paralogues in human: MIR1244-1 (100% identical), MIR1244-2 (100% identical), MIR1244-4 (100% identical).
Diseases named in the same sentence as MIR1244-3 in open-access papers:
MIR1244-3 is named in the same sentence as 1 disease in open-access papers, as found by Europe PMC text mining. Sharing a sentence is not in itself a finding about the gene and the disease. The quoted sentences say what the papers report.
tumor (1 paper, 2021). "The heatmap showed that 12 tumor suppressors formed into two clusters: cluster 1 contains seven downregulated tumor suppressors including PTEN, PSME1, DNAJB1, HSPH1, DEDD2, PAK1IP1, and MIR1244-3; and cluster 2 contains five upregulated tumor suppressors (OSGIN1, IFI27L1, MTCH2, NKD2, and IBTK)." (PMID 34571936, 2021).